INS (insulin)
Diseases named in the same sentence as INS in open-access papers (continued):
Sharing a sentence is not in itself a finding about the gene and the disease.
Insulin resistance (continued). "There has been a strong, positive association between insulin resistance or hyperinsulinemia and hyperuricemia and insulin is shown to decrease eGFR levels." (PMID 20798877, 2010). "Fourth, in insulin resistance, expression levels of molecules implicated in insulin-induced GLUT4 translocation are decreased." (PMID 21187969, 2010). "Insulin resistance is associated with impaired endothelial-mediated vasodilation due both to insulin inability to stimulate NO synthesis and enhanced NO consumption." (PMID 21135801, 2010). "Hypertension is associated with insulin resistance and this relation can partly be explained by decreased capillary density and impaired capillary recruitment seen in insulin resistant states." (PMID 20634940, 2010). "To better understand the relationship between body fat and insulin resistance, we measured the expression of genes associated with energy homeostasis and insulin regulation using a gene array containing 384 genes linked to obesity and insulin resistance." (PMID 20307313, 2010). "Insulin resistance can arise via different mechanisms e.g. mutations in genes encoding insulin signaling components or their reduced expression." (PMID 20463885, 2010). "Since TNF-α has been linked to obesity associated insulin resistance, we assessed plasma glucose, insulin and HOMA in CONV mice fed HF or LF diet and tested for correlations with ileal TNF-α." (PMID 20808947, 2010). "Steatosis is present in most patients with insulin resistance, suggesting that dysfunction of insulin signaling is closely associated with excessive accumulation of lipid in the liver." (PMID 21274430, 2010). "Further studies on the phosphorylation of JNK and insulin pathway signaling factors will provide better insight into alcohol- and CR-induced insulin sensitivity and HF-associated insulin resistance." (PMID 20307313, 2010). "This inflammation causes or worsens insulin resistance in insulin-responsive tissues such as adipose tissue, muscle, or liver." (PMID 20339530, 2010). "It is apparent that for maintaining glucose values within normal range, a much higher level of insulin is needed in PCOS subjects due to insulin resistance and therefore, hyperinsulinemia is a common association with PCOS." (PMID 21234175, 2010). "Fat can cause insulin resistance by prompting the activation of select serine kinases within a variety of insulin sensitive cells." (PMID 20426802, 2010). "Glucocorticoids antagonize insulin signaling in various tissues and thus implicated in the development of insulin resistance." (PMID 21083914, 2010). "BPA exposure aggravated the insulin resistance produced during pregnancy and was associated with decreased glucose tolerance and increased plasma insulin, triglyceride, and leptin concentrations relative to controls." (PMID 20488778, 2010). "Insulin sensitivity (Matsuda model) also decreased in rs4986790 G allele carriers (AG: −0.99%, GG: −10.50%), and insulin resistance (HOMA-IR) accordingly increased (AG: +0.96%, GG: +2.07%)." (PMID 21125016, 2010). "Sustained mTORC1 activity leading to ER stress and JNK activation caused insulin resistance, while treatment with chemical chaperones prevented the ER stress response and enhanced insulin signaling in TSC-deficient cells." (PMID 19305497, 2009). "Considering the association between insulin resistance and AD, we investigated if HN influences insulin sensitivity." (PMID 19623253, 2009). "Considerable evidence implicates insulin resistance in the pathogenesis of AD and underlies current efforts to treat AD by improving insulin sensitivity." (PMID 19523444, 2009). "Insulin resistance is caused by defects in the signaling pathways that process the insulin signal in its target tissues." (PMID 19794883, 2009).
Insulin resistance (continued). "We aimed to unravel the earliest molecular changes associated with the development of insulin resistance as a result of overnutrition and to determine if acute bouts of caloric excess, before weight gain occurs, can lead to changes in insulin signaling." (PMID 19781106, 2009). "High concentrations of circulating fatty acids have a disruptive effect on insulin signalling pathways causing insulin resistance and the manifestation of T2DM in humans." (PMID 19503617, 2009). "Insulin-resistance and type 2 diabetes are risk factors for atherosclerosis and are characterized by high concentrations of insulin and/or glucose." (PMID 20030821, 2009). "To investigate the mechanism by which ATZ-induced mitochondrial dysfunction caused insulin resistance, we analyzed insulin-stimulated Akt phosphorylation in ATZ-treated L6 muscle cells." (PMID 19365547, 2009). "Recently, a link has been established between peripheral insulin sensitivity and the retinol (vitamin A) metabolism, and insulin resistance in rodents and humans has been linked to abnormalities of the vitamin A signaling pathway." (PMID 19460132, 2009). "The suppression of insulin-mediated Akt phosphorylation is clearly linked to the development of insulin resistance in vitro and in vivo." (PMID 19365547, 2009). "Whereas absent initial rise of insulin release is a hallmark of T2DM, elevated basal insulin release is characteristic of T2DM individuals with insulin resistance." (PMID 19607692, 2009). "Linagliptin is expected to be one of the most appropriate therapies for Japanese patients with DM, as deficient insulin secretion is a greater concern than insulin resistance in this population." (PMID 19732457, 2009). "Elevated Foxo1, which occurs under conditions of both insulin absence (type 1 diabetes) and insulin resistance (type 2 diabetes), is associated with increased triglyceride production in mice." (PMID 19424489, 2009). "Type 2 diabetes is often linked to obesity-related insulin resistance, which initially is compensated by enhanced capacity of β cells to secrete insulin." (PMID 19135240, 2009). "Since rare mutations in this gene lead to insulin resistance and lipodystrophy, variations in this gene are likely to contribute to type 2 diabetes susceptibility through altered insulin effects in adipose tissue." (PMID 19794883, 2009). "In such states, ceramides cause insulin resistance by activating pro-inflammatory cytokines and inhibiting insulin-stimulated signaling through PI3 kinase-Akt." (PMID 19742171, 2009). "It damages mitochondrial function, affects insulin signaling, and induces insulin resistance and obesity, especially when exposure is associated with a high-fat diet." (PMID 19365547, 2009). "Serum levels of C-peptide, a subunit of insulin that provides a clinically useful indication of insulin production and the degree of insulin resistance, have been associated with an increased breast cancer risk." (PMID 19545451, 2009). "Reduction in the sensitivity to the peripheral and central actions of insulin (insulin resistance) is associated with several of the most frequent and prevalent human disorders, including type 2 diabetes mellitus, obesity and dyslipidemia." (PMID 18301746, 2008). "In studies of muscles from insulin-deficient rats or db/db mice (a model of insulin resistance), we found that accelerated muscle protein degradation increases the level of the proapoptotic factor, Bax." (PMID 17987322, 2008). "Some PIs including indinavir, have been associated with insulin resistance and an improvement in insulin sensitivity has been observed in some studies when PIs were switch to NNRTI or abacavir." (PMID 18945352, 2008). "Elevated levels of circulating fattyacids, associated with obesity and insulin resistance, increase fataccumulation in insulin target tissues and contribute to defective insulinaction." (PMID 18288286, 2008).
Insulin resistance (continued). "As a result, the diffusion of insulin and its metabolic substrates is delayed and diminished, further aggravating the underlying insulin resistance." (PMID 18949082, 2008). "Inhibition of IKBKB with salicylates or through targeted gene disruption causes a dramatic improvement of insulin sensitivity in animal models of insulin resistance such as ob/ob mice and obese Zucker fatty rats." (PMID 18570670, 2008). "Increased expression of p85α has been implicated in insulin resistance as knockout of p85α improves insulin sensitivity in vitro and in vivo." (PMID 19011679, 2008). "These inflammatory mediators disrupt the insulin signaling pathway and predispose to insulin resistance." (PMID 18570670, 2008). "These datasuggest that the defective insulin-mediated intracellular signal transduction isnot the only cause responsible for insulin resistance, and that the molecularmechanisms of insulin resistance are not completely understood." (PMID 18604303, 2008). "The complexity of these interactions is great because increased glucocorticoids can cause insulin insensitivity, and both insulin deficiency and insulin resistance increase glucocorticoid production." (PMID 17987322, 2008). "High salt diet combined with genetic differences along the insulin signaling and inflammatory pathways predict a powerful inflammatory response and susceptibility to high salt-induced insulin resistance in Dahl S rats." (PMID 18570670, 2008). "Perhaps the causal variants in these genes controlling insulin secretion and insulin resistance are yet to be identified." (PMID 18598350, 2008). "For example, nitric oxide (NO) has been implicated in mediating insulin resistance, as iNOS knockout mice are more sensitive to insulin and more resistant to diet-induced obesity than wild-type mice." (PMID 19007436, 2008). "The overall net effect of GK variants in the BN.GK-Nidd/gk1 congenics on insulin secretion contributes to hyperinsulinaemia and possibly insulin resistance." (PMID 18698428, 2008). "Yet another reason for the delay is the misconception that type 2 DM is a disorder caused by insulin resistance alone and therefore insulin administration is irrational." (PMID 19902051, 2008). "It is also unclear to what extent the unique lifestyle and history of the Amish impacts the contribution of TAS2R variants to manifestations of dysregulated glucose and insulin homeostasis, including the development of insulin resistance and T2DM." (PMID 19092995, 2008). "While the wide range of fat acids has been related with the increase in risk for insulin resistance, the long chain polyunsaturated fat acid omega-3, found in large quantity in fish oil, has been pointed as insulin sensitizing." (PMID 18986529, 2008). "Experiments using mouse models have shown a role for Apo A-II in glucose homeostasis: Apo A-II-deficient mice showed improved insulin sensitivity, whereas transgenic mice over-expressing murine Apo A-II showed insulin resistance and obesity." (PMID 19077222, 2008). "Overall, SAD showed a slightly higher correlation with most cardiovascular risk factors, especially insulin resistance, insulin, CRP, apolipoprotein B and triglycerides (all P-values < 0.01) than other anthropometric measures." (PMID 17391519, 2007). "A preliminary diagnostic criterion for insulin resistance is high levels of plasma insulin in relation to glucose levels." (PMID 17437648, 2007). "Adiponectin improves insulin sensitivity, and reduced adiponectin is associated with insulin resistance, hypertriglyceridemia, and fat redistribution in HIV patients treated with HAART." (PMID 17597538, 2007). "Leptin is suggested to increase insulin sensitivity or to cause insulin resistance and obesity is associated with leptin resistance and a decreased transport of leptin across the blood-brain barrier." (PMID 17311679, 2007).
Insulin resistance (continued). "In general, SAD was a stronger predictor of cardiovascular risk factors, especially of insulin resistance, apoB, insulin, triglycerides and CRP, than the other anthropometric measures." (PMID 17391519, 2007). "According to this view, ENPP1 over-expression in liver and muscle, two main tissues involved in insulin-mediated regulation of glucose and lipid metabolism, determines insulin resistance and susceptibility to type 2 diabetes." (PMID 17849011, 2007). "It is very likely that primary and limited insulin resistance in which loss of peripheral sensitivity and raised insulin levels compensate each other can be good for health and longevity." (PMID 17437648, 2007). "This increased accumulation of fat in skeletal muscle of patients with HIV and lipodystrophy is associated with insulin resistance; there was an inverse relationship between insulin action and intramyocellular lipid content." (PMID 17634130, 2007). "Incremental adjustment for BMI, waist and insulin allows disentangling confounding effects by these variables since adiposity and/or insulin resistance are known to be associated both with most of the considered CVD risk factors and IGR." (PMID 17958881, 2007). "In patients with NAFLD we previously demonstrated a very significant association between A2M and insulin levels, a hallmark of insulin resistance." (PMID 17096854, 2006). "Recently, elevated ADMA concentrations have been linked to metabolic variables related to cardiovascular risk factors like glucose, insulin and insulin resistance, and glucose per se has been shown important in the regulation of DDAH and ADMA." (PMID 16396682, 2006). "In humans, fasting insulin levels correlate positively with androgen levels, and some studies have shown that hyperandrogenism causes insulin resistance in humans and in rats." (PMID 16146570, 2005). "Direct correlation between plasma insulin levels and blood pressure levels has been demonstrated and there is evidence to suggest a causal relationship between insulin resistance with resultant hyperinsulinemia and hypertension." (PMID 16018812, 2005). "(ii) Increase in the level and activity of several tyrosine phosphatases (PTP1B) was found to be associated with insulin resistance and reduced insulin sensitivity." (PMID 15291972, 2004). "A substantial and increasing proportion of death and disability in the EU (and elsewhere) is attributable to diseases associated with insulin resistance (i.e., decreased insulin sensitivity)." (PMID 12805674, 2001). "Insulin resistance was found to be the outcome of reduced activation of muscle insulin receptor tyrosine kinase by insulin, in association with diminished GLUT4 protein and DNA content and overexpression of PKC isoenzymes, notably of PKCepsilon." (PMID 11795838, 2001). "The reasons underlying defective insulin secretion and insulin resistance, which are still under investigation, are complex and beyond the scope of this article." (PMID 15706798, 1998). "Moreover, increased ghrelin (GHRL) levels were associated with improved insulin sensitivity, consistent with previous findings that ghrelin attenuates insulin resistance in women with PCOS." (PMID 41514462, 2026). "In addition, the treatment significantly reduced insulin resistance caused by a high‐fat diet and restored insulin sensitivity." (PMID 41497732, 2026). "Six studies reported significant associations between low vitamin D levels and markers of insulin resistance, including a positive correlation with estimated glucose disposal rate (eGDR), as well as associations with higher insulin requirements and greater odds of insulin resistance." (PMID 42058333, 2026). "Taken together, these findings suggest that circulating irisin is closely linked to lipid metabolism and insulin sensitivity, with its associations shifting from predominantly lipid-related in prediabetes to both lipidic and insulin-resistance–related in overt T2DM." (PMID 41596434, 2026).
Insulin resistance (continued). "Additionally, high fasting insulin and insulin resistance have been associated with high prevalence of thyroid carcinoma in a meta-analysis of 14 global case-control studies." (PMID 41376649, 2026). "Individuals with a TG/HDL ratio > 2 and increased urinary kynurenate excretion exhibited a 3.6-fold higher relative risk of insulin resistance, while elevated insulin levels combined with urinary α-ketoisovalerate were associated with a 2.7-fold increased risk." (PMID 41751292, 2026). "This hypothesis underscores hepatic insulin clearance as a potential mediator of insulin resistance and its role in diseases linked to chronic hyperinsulinemia." (PMID 42227093, 2026). "Linear regression was used to examine the associations between DAL and fasting blood glucose, fasting insulin levels, estimated glucose disposal rate (eGDR), Homeostasis Model Assessment of Insulin Resistance (HOMA-IR), and the TyG index in the affected population." (PMID 41952767, 2026). "Adiponectin enhances insulin sensitivity, so blocking its receptors (AdipoRs) could reduce insulin sensitivity, potentially contributing to insulin resistance and increasing the risk of type 2 diabetes." (PMID 40426884, 2025). "Consequently, as these cells become damaged and lose their functional capacity, they are unable to produce and release sufficient insulin to counteract peripheral insulin resistance, which is a hallmark of type 2 diabetes." (PMID 40958722, 2025). "This group shows a lower BMI than SIRD and MOD, severe insulin resistance, a high level of insulin secretion, good metabolic control, a high risk of developing metabolic-associated fatty liver disease (MAFLD), and a similar risk to SIRD of CKD, although lower than MOD." (PMID 41255523, 2025). "Maintaining a certain amount of alcohol consumption for a long time may lead to decreased insulin sensitivity, enhance insulin resistance, and increase the risk of ASIR." (PMID 40219013, 2025). "Insulin resistance is a central pathological characteristic of type 2 diabetes and metabolic syndrome, and its manifestation is intricately linked to dysregulation of the insulin signaling pathway." (PMID 40740995, 2025). "Albeit within the normal range, BMI was inversely associated with insulin action, suggesting that even a relative increase in body weight within the normal range may be responsible, at least in part, for insulin resistance." (PMID 39998445, 2025). "In line with our study, it has been shown that the increase in fasting glycemia levels in ovariectomized rats consuming a high-fat diet can be linked to elevated insulin resistance and decreased insulin sensitivity caused by excessive deposition of visceral fat." (PMID 40343300, 2025). "Moreover, aging is associated with decreased insulin sensitivity, which promotes insulin resistance." (PMID 41267995, 2025). "The exact mechanism by which ADPKD leads to NODAT remains unclear, but mutations in the PKD1 and PKD2 genes, which are associated with the disease, may contribute to insulin resistance, impaired insulin secretion, and gluconeogenesis." (PMID 39941214, 2025). "In contrast, T2DM (non-insulin dependent) is caused by the low production of insulin or the inability of cells, especially muscle and adipose tissue, to respond to the insulin produced (insulin resistance), thus lowering the glucose clearance from the blood." (PMID 41154479, 2025). "Although we can observe associations between them, determining whether increased insulin resistance leads to depression, whether depression contributes to changes in insulin sensitivity, or if a bidirectional relationship exists, remains challenging." (PMID 39911326, 2025). "Insulin resistance caused by obesity and/or insulin signaling aberrations may lead to compensatory hyperinsulinemia in some PCOS patients, consistent with the prevailing paradigm." (PMID 40013621, 2025).